CAMP (cathelicidin antimicrobial peptide)
Description:
Antimicrobial protein that is an integral component of the innate immune system. Binds to bacterial lipopolysaccharides (LPS). Acts via neutrophil N-formyl peptide receptors to enhance the release of CXCL2. Postsecretory processing generates multiple cathelicidin antimicrobial peptides with various lengths which act as a topical antimicrobial defense in sweat on skin. The unprocessed precursor form, cathelicidin antimicrobial peptide, inhibits the growth of Gram-negative E.coli and E.aerogenes with efficiencies comparable to that of the mature peptide LL-37 (in vitro). [Antibacterial peptide LL-37]: Antimicrobial peptide that is an integral component of the innate immune system. Binds to bacterial lipopolysaccharides (LPS). Causes membrane permeabilization by forming transmembrane pores (in vitro). Causes lysis of E.coli. Exhibits antimicrobial activity against Gram-negative bacteria such as P.aeruginosa, S.typhimurium, E.aerogenes, E.coli and P.syringae, Gram-positive bacteria such as L.monocytogenes, S.epidermidis, S.pyogenes and S.aureus, as well as vancomycin-resistant enterococci (in vitro). Exhibits antimicrobial activity against methicillin-resistant S.aureus, P.mirabilis, and C.albicans in low-salt media, but not in media containing 100 mM NaCl (in vitro). Forms chiral supramolecular assemblies with quinolone signal (PQS) molecules of P.aeruginosa, which may lead to interference of bacterial quorum signaling and perturbance of bacterial biofilm formation. May form supramolecular fiber-like assemblies on bacterial membranes. Induces cytokine and chemokine production as well as TNF/TNFA and CSF2/GMCSF production in normal human keratinocytes. Exhibits hemolytic activity against red blood cells. [Antibacterial peptide FALL-39]: Exhibits antimicrobial activity against E.coli and B.megaterium (in vitro). [Antibacterial peptide KR-20]: Acts synergistically with peptides KS-30 and KR-31, killing bacteria such as S.aureus, E.coli and C.albicans at lower concentrations when present together, and maintains activity at increased salt condition. Does not have the ability to stimulate CXCL8/IL8 release from keratinocytes. [Antibacterial peptide LL-23]: Poorly active (MIC > 150 uM) against E.coli strain K12. Is able to induce the pro-inflammatory cytokine TNF/TNFA or the chemokine CCL2/MCP1. [Antibacterial peptide LL-29]: Moderately antibacterial. [Antibacterial peptide KS-30]: Moderately antibacterial. Acts synergistically with peptides KR-20 and KR-31, killing bacteria such as S.aureus, E.coli and C.albicans at lower concentrations when present together, and maintain activity at increased salt condition. Does not have the ability to stimulate CXCL8/IL8 release from keratinocytes. [Antibacterial peptide RK-31]: Acts synergistically with peptides KS-30 and KR-31, killing bacteria such as S.aureus, E.coli and C.albicans at lower concentrations when present together, and maintain activity at increased salt condition. Does not have the ability to stimulate CXCL8/IL8 release from keratinocytes. [Antibacterial peptide FF-33]: Inhibits the growth of E.coli and B.megaterium and exhibits hemolytic activity against human red blood cells.
Synonyms: CAP-18; CAP18; FALL39; HSD26; FALL-39; LL37; CRAMP
Tractability: Small molecule: a structure with a bound ligand is known. Antibody: UniProt places it where antibodies can reach, with high confidence; its Gene Ontology location is reachable by antibodies, with high confidence; UniProt predicts a signal peptide or a membrane-spanning region.
Gene: Protein-coding gene on chromosome 3 (48,223,347 to 48,225,491, forward strand). Ensembl gene ENSG00000164047.
Subcellular location: Secreted; Vesicle
Pathways (Reactome):
Immune System: Antimicrobial peptides; Neutrophil degranulation
Gene Ontology:
Molecular function: protein binding; lipopolysaccharide binding
Biological process: amyloid fibril formation; antibacterial humoral response; antibacterial innate immune response; antimicrobial humoral immune response mediated by antimicrobial peptide; cytolysis; defense response to bacterium; defense response to Gram-positive bacterium; innate immune response in mucosa; neutrophil activation; defense response to Gram-negative bacterium; innate immune response; cellular response to butyrate; cellular response to exogenous dsRNA; cellular response to interleukin-1; cellular response to interleukin-6; cellular response to lipopolysaccharide; cellular response to peptidoglycan; cellular response to tumor necrosis factor; defense response; dentinogenesis; leukotriene biosynthetic process; negative regulation of apoptotic process; positive regulation of angiogenesis; positive regulation of antimicrobial humoral response; positive regulation of cell population proliferation; and 8 more
Cellular component: extracellular exosome; extracellular region; specific granule; vesicle; specific granule lumen; tertiary granule lumen
Genetic constraint (gnomAD): Loss-of-function variants: 8 observed, 11.98 expected, observed/expected ratio (o/e) 0.67, 90% interval 0.39 to 1.2. The upper end of that interval is the gene's LOEUF score, 1.2, which puts it in group 5 of 6, group 1 being the genes least tolerant of losing a copy. Missense variants: 201 observed, 218.02 expected, observed/expected ratio (o/e) 0.92, 90% interval 0.82 to 1.04. Synonymous variants: 86 observed, 88.5 expected, observed/expected ratio (o/e) 0.97, 90% interval 0.81 to 1.16.
Homologues: Orthologues: chimpanzee CAMP (99% identical), macaque CAMP (86% identical), dog CAMP (58% identical), rabbit CAMP (58% identical), rat Camp (58% identical), mouse Camp (55% identical), pig PMAP-23 (51% identical), pig PMAP-36 (51% identical), pig NPG1 (49% identical), pig NPG3-PG-2 (49% identical), guinea pig Camp (45% identical).
Diseases named in the same sentence as CAMP in open-access papers:
CAMP is named in the same sentence as 295 diseases in open-access papers, as found by Europe PMC text mining. Sharing a sentence is not in itself a finding about the gene and the disease. The quoted sentences say what the papers report.
psoriasis (164 papers, 2009 to 2026). An autoimmune condition characterized by red, well-delineated plaques with silvery scales that are usually on the extensor surfaces and scalp. "The protein encoded by CAMP belongs to the antimicrobial peptide group that was previously established to be an autoantigen in psoriasis which is involved in cell chemotaxis, inflammatory response regulation and immune mediator induction." (PMID 33758323, 2021). "The human cathelicidin antimicrobial peptide (CAMP or LL37) is another well-known antimicrobial peptide shown to induce immunomodulatory effects and has been found to be associated with immune-related disorders like psoriasis and morbus Kostmann." (PMID 29970096, 2018). "This study examined changes in skin mRNA expression of L-kynureninase (Kynu), cathelicidin antimicrobial peptide (Camp), beta-defensin 2 (Defb2), and proenkephalin (Penk) in a mouse model of imiquimod-induced psoriasis." (PMID 39045230, 2024). "Two downregulated genes (BPIFB1 and CAMP) in this group had been reported to be involved in interstitial lung disease, psoriasis, rosacea, or other skin inflammatory disorders." (PMID 31068931, 2019). "Expression of the gene encoding cathelicidin antimicrobial peptide (CAMP), whose expression has been reported to increase in psoriasis, was also found to increase by 2.4-fold in our lesional skin substitutes." (PMID 30261611, 2018). "First, we identified a psoriasis-like expression response in KCs treated in vitro with cathelicidin antimicrobial peptide (CAMP/LL37)." (PMID 26251673, 2015). "A recent report found that IL-17A augmented vitamin D3-mediated CAMP production in keratinocytes during psoriasis." (PMID 22174673, 2011). "Similar to HBD2, cathelicidin antimicrobial peptide has been suggested to play an important role in psoriasis pathogenesis." (PMID 19623255, 2009). "In psoriasis, moreover, the cytokines IL-17, IL-22, TNF-α and IFN-γ promote the secretion of antimicrobial peptides (AMPs) such as human β-defensins and the cathelicidin LL-37 (encoded by CAMP) by keratinocytes." (PMID 38251799, 2024). "The pleiotropic multifunctional 37 amino acid molecule LL37, which is generated by extracellular cleavage of the C-terminal part of the 170 amino acid Cathelicidin antimicrobial peptide was proposed a potential autoantigen because LL37 peptides induced strong T-cell responses in psoriasis." (PMID 29760713, 2018). "However, in the presence of antimicrobial peptides (AMP), such as LL37 (or CAMP), B-defensins and Ribonuclease 7, inert self-DNA can be converted into potent autoantigen triggering IFNα production by pDCs, and driving autoimmunity in psoriasis." (PMID 35207521, 2022). "CAMP was among PP-increased DEGPs identified in this study and may have important auto-antigen activity in psoriasis, either by forming complexes with self-derived nucleic acids to trigger innate immune responses, or by interacting with and stimulating T cells." (PMID 26251673, 2015). "CAMP and DEFB2 are two types of AMPs secreted by keratinocytes in psoriasis." (PMID 39045230, 2024). "The antimicrobial peptide LL-37 (also known as cathelicidin antimicrobial peptide, CAMP) is overexpressed in psoriatic lesions and acts as the critical factor that mediates plasmacytoid dendritic cells (pDCs) activation in psoriasis." (PMID 36118867, 2022).
rosacea (47 papers, 2013 to 2025). A chronic erythematous skin disorder that affects the face. "In particular, human cathelicidin antimicrobial peptide (CAMP) plays a critical role in rosacea pathogenesis, exhibiting both immunomodulatory and angiogenic properties." (PMID 40149947, 2025). "Human cathelicidin antimicrobial peptide (CAMP) is intimately involved in the pathogenesis of rosacea, with both immunomodulatory and angiogenic properties." (PMID 38450615, 2024). "CAMP RNA and protein expression was also higher in the skin of patients with rosacea than in healthy controls." (PMID 27649161, 2016). "Patients with rosacea also exhibit abnormally high levels of kallikrein-5 (KLK5), a serine protease that processes CAMP into bioactive fragments such as LL-37, thereby amplifying the inflammatory cascade." (PMID 40149947, 2025). "The increased abundance of CAMP and KLK5 activity has been shown to increase the levels of bioactive cathelicidin fragments in rosacea patients." (PMID 38450615, 2024). "Elevated levels of disease characteristic factors, such as KLK5, CAMP, TLR2, and proinflammatory cytokines (such as TNF‐α, IL1β, and IL6), and MMPs have been observed in the skin lesions of human rosacea patients as well as in a mouse model of rosacea induced by LL37." (PMID 39692542, 2024).
Sepsis (36 papers, 2007 to 2025). Sepsis is defined as life-threatening organ dysfunction caused by a dysregulated host response to infection. "Mice that had been infected with sublethal doses of GBS developed fatal septicemia after receiving repeated injections with purified CAMP factor." (PMID 21533261, 2011). "The subsequent growth of the CAMP-resistant population leads to septicemia and insect death." (PMID 28252016, 2017). "The induction of CAMP and other antimicrobial genes suggested that 1,25(OH)2D3 might be protective against sepsis after injury and might accelerate epithelial wound healing." (PMID 17397543, 2007). "An additional limitation of this study is that we did not assess the role of GBS CAMP factor in polymicrobial infections with S. aureus in an invasive context such as sepsis, which is beyond the scope of this work." (PMID 34908468, 2021). "CAMP, an antimicrobial peptide, is upregulated in both infectious and non-infectious inflammatory states, and its expression is not exclusive to sepsis-similar changes, which can also be observed in other inflammation-related diseases (e.g., pneumonia, rheumatic diseases)." (PMID 41259376, 2025). "Thus, the upregulation of CAMP in sepsis likely reflects general inflammatory activation rather than sepsis-specificity." (PMID 41259376, 2025).
systemic lupus erythematosus (33 papers, 2009 to 2026). An autoimmune multi-organ disease typically associated with vasculopathy and autoantibody production. "It has been widely accepted that CAMP has an important role in inflammatory-related diseases such as chronic inflammatory skin disease, Crohn’s disease, and autoimmune diseases including psoriatic arthritis, systemic lupus erythematosus, and atherosclerosis." (PMID 32365569, 2020).
atherosclerosis (31 papers, 2006 to 2026). A disease characterized by the build-up of fatty material and calcium deposition in the arterial wall resulting in partial or complete occlusion of the arterial lumen. "It is known that CAMP is produced and secreted by monocytes, which—like macrophages—are involved in the development of atherosclerosis." (PMID 38474156, 2024). "The present study aimed to investigate levels of CAMP/CRAMP, an antimicrobial peptide regulated by inflammatory and metabolic parameters, in the context of atherosclerosis, a disease caused by inflammatory and metabolic factors." (PMID 38474156, 2024). "We investigated systemic CAMP/CRAMP levels in experimental murine models of atherosclerosis, myocardial infarction and cardiovascular patients." (PMID 38474156, 2024). "CAMP is also produced in atherosclerotic lesions, where it may enhance the innate immune response in atherosclerosis." (PMID 38474156, 2024). "Recently, CAMP was described to play a role in atherosclerosis." (PMID 38474156, 2024). "In summary, we determined that ITGAM, TYROBP, ICAM1 and CAMP may possess significant roles in mediating the chronic inflammatory process that eventually culminates in atherosclerosis and CAD." (PMID 33758323, 2021). "Amounts of LL-37-mtDNA complex increased in atherosclerotic plasma and plaques, resisted DNase II degradation, and escaped from autophagic recognition in atherosclerosis, indicating that CAMP might induce atherosclerosis to increase the risk of CHD." (PMID 34692829, 2021). "Our results verified that CAMP, LYZ, and PGLYRP1 were important factors in constituting the atherosclerosis of CHD." (PMID 34692829, 2021). "Since we could demonstrate a significant influence of HFD-induced atherosclerosis and myocardial infarction on circulating CRAMP levels in the experimental mouse models, we investigated CAMP serum levels in CAD patients in a translational approach." (PMID 38474156, 2024).
breast carcinoma (29 papers, 2009 to 2025). "Our data implicated that CAMP confers an oncogenic role in breast cancer and plays an important role in the tumor microenvironment between TAMs and breast cancer cells, and blocking the interaction between them would provide a novel therapeutic option for this malignant disease." (PMID 32365569, 2020). "Co-culture of breast cancer cells with M2 macrophages promoted cancer cell proliferation and was abated in the cancer cells co-cultured with CAMP-deficient macrophages with increased CAMP and P2X7 expressions." (PMID 32365569, 2020). "The results demonstrated that the expression levels of OLR1, ADIPOR1, CEACAM6, DNASE2, CD53, BMF, and CAMP were significantly elevated in breast cancer samples compared to healthy controls (p < 0.05)." (PMID 40282270, 2025). "CAMP in breast cancer cells also induces the production of cytokines through interacting macrophages." (PMID 39351437, 2024). "CAMP displays a tumorigenic effect in ovarian cancer, lung cancer, breast cancer, prostate cancer, pancreatic cancer, malignant melanoma, and skin squamous cell carcinoma." (PMID 37958632, 2023). "The Western blotting result showed CAMP protein expression increased in both macrophages and breast cancer cells after co-culture for 5 days." (PMID 32365569, 2020). "With cut-off of 2-fold, we found that CAMP is one of the most upregulated genes in breast cancer which was further confirmed by qRT-PCR." (PMID 32365569, 2020). "CAMP peptide concentration was increased in medium during co-culture of breast cancer cells and macrophages." (PMID 32365569, 2020). "To further delineate the role of CAMP in the transition to M2 macrophages when co-cultured with breast cancer cells, we used A438079 pre-treated THP-1 cells for macrophage differentiation, aiming to block the effect of CAMP during this process." (PMID 32365569, 2020). "To further investigate the role of CAMP on tumor growth, we developed a CAMP-stable overexpressing breast cancer cell line." (PMID 32365569, 2020). "First, we analyzed the CAMP mRNA expression between breast cancer (BC) tissues and normal tissues (NC) using the publicly available TCGA database." (PMID 32365569, 2020). "In the CAMP-deficient macrophage group (A438079 pre-treated group), M2 marker ARG-1 expression was decreased when compared to the control group co-culture with breast cancer (BC) cells." (PMID 32365569, 2020). "For example, CAMP was also known to be upregulated in breast cancer tissues compared to normal tissues." (PMID 32365569, 2020). "Knockdown of CAMP decreased cell proliferation and migration/invasion ability in breast cancer cells." (PMID 32365569, 2020). "Then, we further validated in our cohort that the expression level of CAMP was higher in breast cancer patients’ tissues (T) when compared to their paired normal tissues (TN) and normal control tissues (NC)." (PMID 32365569, 2020). "Breast cancer cells showed differential basal CAMP gene expression depending on the cell phenotype: ERα + breast cancer cells showed the highest while ERα- the lowest." (PMID 27832772, 2016). "Our results suggest that calcitriol anti-cancer therapy is more likely to induce higher levels of CAMP in ERα- breast cancer cells when compared to ERα + breast cancer cells." (PMID 27832772, 2016). "In particular, ERα + breast cancer cells showed the highest basal CAMP gene expression, while the lowest was obtained in ERα- cells." (PMID 27832772, 2016). "CAMP and its inhibitors 8-Cl-cAMP induce tumor cells’ apoptosis, enhance p21, p27 levels, inhibit breast cancer, prostate cancer, ovarian cancer and colon cancer growth." (PMID 24351817, 2013). "Additionally, previous research has confirmed the roles of these five central genes (CEACAM6, CAMP, PNPLA2, OLR1, and ADIPOR1) in breast cancer, which were consistent with our predictions of risk and protective factors." (PMID 40282270, 2025). "It has been reported that increased expression of CAMP in human breast cancer." (PMID 39911484, 2024).